EVA1C (eva-1 homolog C)
Description:
Binds heparin.
Synonyms: C21orf63; C21orf64; FAM176C; PRED34; B18; B19; SUE21
Tractability: Antibody: its Gene Ontology location is reachable by antibodies, with high confidence; UniProt predicts a signal peptide or a membrane-spanning region. PROTAC: ubiquitination databases record sites on it.
Gene: Protein-coding gene on chromosome 21 (32,411,710 to 32,517,158, forward strand). Ensembl gene ENSG00000166979.
Subcellular location: Membrane
Subcellular location (Human Protein Atlas): Cytosol
Gene Ontology:
Molecular function: heparin binding; carbohydrate binding
Cellular component: extracellular region; membrane
Genetic constraint (gnomAD): Loss-of-function variants: 23 observed, 36.21 expected, observed/expected ratio (o/e) 0.64, 90% interval 0.46 to 0.9. The upper end of that interval is the gene's LOEUF score, 0.9, which puts it in group 3 of 6, group 1 being the genes least tolerant of losing a copy. Missense variants: 436 observed, 484.57 expected, observed/expected ratio (o/e) 0.9, 90% interval 0.83 to 0.97. Synonymous variants: 177 observed, 194.06 expected, observed/expected ratio (o/e) 0.91, 90% interval 0.81 to 1.03.
Homologues: Orthologues: chimpanzee EVA1C (98% identical), macaque EVA1C (97% identical), dog EVA1C (91% identical), pig EVA1C (89% identical), mouse Eva1c (86% identical), guinea pig EVA1C (82% identical), rat Eva1c (76% identical), zebrafish eva1c (40% identical), Caenorhabditis elegans mth-1 (28% identical), Drosophila melanogaster mthl14 (17% identical). Paralogues in human: ADGRB2 (18% identical), ADGRL2 (16% identical), ADGRL3 (16% identical), ADGRG4 (16% identical), ADGRG2 (15% identical), ADGRE2 (15% identical), ADGRB1 (15% identical), ADGRL1 (15% identical), ADGRE5 (15% identical), ADGRF5 (15% identical), ADGRG6 (15% identical), ADGRB3 (15% identical), and 30 more.
Diseases named in the same sentence as EVA1C in open-access papers:
EVA1C is named in the same sentence as 13 diseases in open-access papers, as found by Europe PMC text mining. Sharing a sentence is not in itself a finding about the gene and the disease. The quoted sentences say what the papers report.
glioma (2 papers, 2021 to 2023). A benign or malignant brain and spinal cord tumor that arises from glial cells (astrocytes, oligodendrocytes, ependymal cells). "In patients with World Health Organization (WHO) grade II/III glioma, high EVA1C expression was associated with malignant clinicopathological features and poor overall survival in both cohorts." (PMID 34267752, 2021). "Furthermore, EVA1C was considered as a risk factor for glioma patients as Kaplan-Meier curves showed that the high EVA1C expression group presented poorer prognosis than the low expression group." (PMID 34267752, 2021). "The EVA1C expression in different tumors cell lines was obtained from CCLE database, it was also confirmed that EVA1C was highly expression in glioma cell lines." (PMID 34267752, 2021). "In this study, we observed for the first time that EVA1C was significantly overexpressed in glioma, and significantly correlated with malignant clinicopathological features." (PMID 34267752, 2021). "Firstly, we compared the differences in EVA1C expression between glioma and normal brain tissues by GEPIA website, and found that the mRNA levels of EVA1C were upregulated in glioblastoma (GBM)." (PMID 34267752, 2021). "For the first time, we identified the overexpression of EVA1C in glioma, which was tightly correlated with the high infiltration levels of multiple immune cells as well as poor prognosis." (PMID 34267752, 2021). "In summary, we found that EVA1C expression was upregulated in glioma compared with normal brain tissues, and the elevated expression level was significantly associated with malignant features and poor prognosis of glioma patients." (PMID 34267752, 2021). "This association indicates that two member of EVA family, EVA1B and EVA1C, might have a role in prognosticating elevated levels of immune infiltration within glioma." (PMID 37808305, 2023). "These outcomes reveal that EVA1C protein may increase the recruitment of immune cells in WHO grade II/III glioma." (PMID 34267752, 2021). "Meanwhile, EVA1C might be a potential biomarker for predicting high immune infiltration in WHO grade II/III gliomas." (PMID 34267752, 2021). "Meanwhile, we focused on the correlation between EVA1C expression and abundance of immune infiltrates by immune profiles, and further investigate whether EVA1C could act as a new immune marker for assessing immune microenvironment of glioma patients." (PMID 34267752, 2021). "Herein, our study was aimed to identify the EVA1C expression and its correlation with clinicopathological factors, and survival prognosis of patients with WHO grade II/III glioma." (PMID 34267752, 2021). "To identify the role of EVA1C in glioma, we statistically analyzed the correlation between EVA1C expression and clinicopathological features as well as prognosis in the CGGA cohort of 182 patients with WHO grade II/III glioma." (PMID 34267752, 2021). "A key finding in our study is that high EVA1C expression correlates with the high abundance of immune infiltrates including B cells, CD4+ T cells, neutrophils, macrophages and DCs in WHO grade II/III glioma." (PMID 34267752, 2021). "However, it is still unclear whether the expression of EVA1C is related to the efficacy of immunotherapy and chemotherapy for glioma, and there is no data in this regard at present." (PMID 34267752, 2021). "However, what is the role of EVA1C plays in glioma is not reported." (PMID 34267752, 2021).
tauopathy (2 papers, 2025 to 2026). Neurodegenerative disorders involving deposition of abnormal tau protein isoforms (tau proteins) in neurons and glial cells in the brain. "Functionally, hippocampal knockdown of Eva1c abolishes the memory improvement induced by NAD+ supplementation in tauopathy mouse and worm models, demonstrating that EVA1C is essential for the cognitive and proteostatic benefits of NAD+." (PMID 41313318, 2026). "This encouraged us to further explore the possible role of Eva1c in tauopathy disease progression in the mouse." (PMID 41202143, 2025). "To clarify the roles and contribution of EVA1C to AD pathology and progression, we used several tauopathy models including human SH-SY5Y cells overexpressing 2N3R Tau, hTau[P301L] C. elegans, hTau.P301S mice, and human brain tissue." (PMID 41202143, 2025). "This study demonstrates that NAD+-induced differential expression of Eva1c/EVA1C isoforms and events downstream of EVA1C contribute to NAD+’s neurological benefits in experimental models of AD-like tauopathies." (PMID 41202143, 2025). "In human cell and mouse models of tauopathy, NAD+ supplementation increases BAG1 and HSPA/HSP70 abundance and strengthens their interaction with EVA1C." (PMID 41313318, 2026). "This analysis led us to focus on interactions between EVA1C, HSP70, and BAG1, which were subsequently validated in selected experimental models of tauopathy." (PMID 41202143, 2025). "We further designed experiments to explore the pathway(s) and effectors downstream of EVA1C in the presence or absence of NR in tauopathy mice." (PMID 41202143, 2025). "Consistent with the cell-based results, IF data showed that NR reduced the colocalization between EVA1C/BAG1 in tauopathy mice but not EVA1C/HSP70." (PMID 41202143, 2025). "First, although Eva1c/EVA1C emerged as a significantly regulated splicing target upon NAD+ precursor treatment, we did not examine whether knockdown or knockout of Eva1c alone is sufficient to induce abnormal ASEs similar to those observed in tauopathy models." (PMID 41202143, 2025).
Cirrhosis (1 paper, 2023). A chronic disorder of the liver in which liver tissue becomes scarred and is partially replaced by regenerative nodules and fibrotic tissue resulting in loss of liver function. "The researchers discovered that rs2833856 in the EVA1C (EVA-1 homolog C) gene was associated with chronic HBV susceptibility, whereas rs4661093 in the ETV3 (ETS variant transcription factor three) gene indicated a risk of progression from decompensated cirrhosis to HCC." (PMID 36851773, 2023).
diabetes (1 paper, 2016). "EVA1C is a Slit receptor involved in Robo-mediated axonal guidance, OLIG2 regulates spinal cord oligodendrocyte and motor neuron development, IFNAR1 is an interferon receptor with no role in the initiation or progression of diabetes and RUNX1 is involved in haematopoiesis." (PMID 27195491, 2016).
Down syndrome (1 paper, 2013). "Given its presence in the Down syndrome critical region and the similarities in the defects present in Down Syndrome and Slit/Robo mutant embryos, it is tempting to speculate that Eva1c is associated with Down syndrome." (PMID 24040182, 2013). "Interestingly, the human orthologue of Eva1c (previously referred to as Fam176C or C21orf63) is located within the Down syndrome critical region (21q21-21q22.3)." (PMID 24040182, 2013).
cancer (1 paper, 2021). A tumor composed of atypical neoplastic, often pleomorphic cells that invade other tissues. "Significant correlations between the EVA1C and the markers of TAMs as well as M2 macrophages suggest that EVA1C possesses the potential in regulating the polarization of TAMs, which is crucial for cancer development and metastasis." (PMID 34267752, 2021).
EVA1C also shares sentences with these, for which no sentence is quoted: acute myeloid leukemia (1 paper); glioblastoma (1); pancreatic adenocarcinoma (1); pancreatic cancer (1); renal carcinoma (1); thymoma (1); tumor (1).